BECN1 (beclin 1)
Diseases named in the same sentence as BECN1 in open-access papers (continued):
Sharing a sentence is not in itself a finding about the gene and the disease.
thyroid (1 paper, 2025).
tongue cancer (1 paper, 2015). A malignant neoplasm affecting the tongue. "Secondly, Beclin 1 inhibition in another tongue carcinoma SCC15 also resulted in similar responses to ANE 30–100K as non-infected Pa cells." (PMID 26017803, 2015). "Firstly, by using the same methods without further cloning, Beclin 1 expression could be effectively inhibited in tongue carcinoma SCC25 cells (sh-bec)." (PMID 26017803, 2015).
toxoplasmosis (1 paper, 2010). A parasitic disease contracted by the ingestion or fetal transmission of toxoplasma gondii. "Similar to the studies with Becn1+/− mice, ATG7flox/flox-Lyz-Cre mice were susceptible to toxoplasmosis despite upregulation of IFN-γ, TNF-α and NOS2 mRNA and the generation of T. gondii-specific T cell response." (PMID 21217818, 2010).
tubular carcinomas (1 paper, 2019). "Interestingly, in the low-grade tubular carcinomas only two cases exhibited an immunopositive cytoplasmic reaction for LC3A/B and Beclin 1, whereas four different low-grade cases showed AMBRA-1 positive expression." (PMID 30893939, 2019).
ulcer (1 paper, 2024). "In addition, the levels of Beclin‐1 and LC3 in ulcer granulation tissue of infected DFU patients were strongly reduced." (PMID 38577990, 2024).
urothelial bladder carcinoma (1 paper, 2022). "To further validate the correlations among ATG5/12, Beclin 1, MMP2, and MMP9 in BC, we analyzed urothelial bladder carcinoma datasets on the GEPIA2 web server." (PMID 35449123, 2022).
varicocele (1 paper, 2021). A condition characterized by the dilated tortuous veins of the spermatic cord with a marked left-sided predominance. "In rats, varicocele testes cells showed increased expression of autophagy marker Beclin 1 and microtubule associated protein 1 light chain 3α (LC3) II/LC3I; Exposure of GC-2 cells to hypoxia conditions reduced P62 protein expression and increased the expression of LC3 II and Beclin-1." (PMID 34589489, 2021).
Wolfram syndrome 2 (1 paper, 2013). Any Wolfram syndrome in which the cause of the disease is a mutation in the CISD2 gene. "It was implicated in human pathology (Wolfram Syndrome 2) and in BCL-2 mediated antagonization of Beclin 1-dependent autophagy and depression of ER calcium stores." (PMID 23717386, 2013).
tumor (897 papers, 2009 to 2026). "It has been proposed that BECN1 acts as a tumor suppressor, and more recently, low levels of BECN1 have been linked to a worse prognosis in gastric, colorectal and pancreatic, as well as breast, cancer." (PMID 39996745, 2025). "Other studies support the theory of autophagy pathways as active tumor suppressors, such as those describing the allelic loss of BECN1." (PMID 39129390, 2025). "Its evidence is present when autophagy-associated proteins like ATG5, ATG7, and Beclin-1 are impaired, and then spontaneous tumors are reported, suggesting their tumor suppressive function." (PMID 40444035, 2025). "Specifically, the expression of Beclin-1 can alter the polarization state of tumor-associated macrophages (TAMs), enhancing their immunosuppressive function and thus promoting tumor development." (PMID 39650649, 2024). "Our study, despite the limitation of the small sample size, showed association between decreased BECN1 expression and BC higher tumor grade, warranting further investigations on larger cohort." (PMID 38787424, 2024). "Studies of the BECN1 gene, which encodes beclin-1, provided the first evidence that autophagy plays a tumor suppressor role." (PMID 38933333, 2024). "Research indicates that the regulation of autophagy is closely linked to the survival and death of tumor cells, with the overexpression of Beclin-1 being closely associated with chemotherapy resistance." (PMID 39650649, 2024). "Targeting Beclin-1, an autophagy-related gene, causes functional NK cell infiltration into the tumor microenvironment (TME) by releasing C-C motif chemokine ligand 5 (CCL5)/RANTES from tumor cells." (PMID 38627815, 2024). "In accordance with our study, they found that lower expression in BECN1 (mRNA and protein levels) was associated with poor tumor differentiation." (PMID 38787424, 2024). "Taken together, the acquisition of the shared phenotypes with CAA enables BECN1-deficient adipocytes to form a favorable milieu for tumor growth." (PMID 38744820, 2024). "Implementing our mouse models and BECN1-deficient adipocyte cell lines, we identify the key factors that facilitate the enhanced tumor progression within adipose-rich environments." (PMID 38744820, 2024). "The BECN1 gene, which encodes the autophagic protein Beclin-1, was the first autophagic gene to be described to play a role as a tumor suppressor." (PMID 38612567, 2024). "We reported that B-NHLs in which ≥20% of tumor cells expressed high levels of BECLIN-1 were associated with complete (57%) or partial (35%) remission." (PMID 37566004, 2023). "Clinical studies have revealed that abnormal expression of Beclin 1 in tumor tissues is linked to poor prognosis for certain tumor phenotypes." (PMID 37834333, 2023). "The deletion of ATG5 results in a tumor-suppressive phenotype, akin to the presence of heterozygote mutation of BECN1 in cancer models, whereas only benign hepatomas are observed in a mouse liver model." (PMID 38067169, 2023). "Cancer cell apoptosis or necrosis, inhibition of tumor angiogenesis, and tumor-targeted and beclin-1-induced autophagy are associated with tumor growth inhibition." (PMID 38203467, 2023). "Beclin-1, as the first recognized mammalian autophagic protein, is implicated in autophagy initiation and modulation of several tumor cell signaling pathways." (PMID 37098542, 2023). "Previous studies show that BECN1 ubiquitination is closely associated with autophagy, which results in tumour progression." (PMID 37859585, 2023). "The essential autophagy gene ATG6/BECN1 encoding the Beclin1 protein has been postulated as a tumor suppressor in breast, ovarian, and prostate malignancies." (PMID 37189748, 2023). "Reduced autophagy has been associated with tumor progression, while certain tumor-suppressor proteins regulate autophagy to restrain tumor growth (examples include Beclin-1 and PTEN)." (PMID 37834333, 2023).
tumor (continued). "Further research conducted by Yue and colleagues confirmed that mice with a heterozygous Beclin 1 mutation (Beclin 1+/−) exhibited a high incidence of tumor development." (PMID 37834333, 2023). "Beclin-1 is a protein that is involved in the early stages of autophagy and has been associated with being a tumor suppressor." (PMID 37834467, 2023). "This low expression level of Beclin 1 is also strongly associated with advanced tumor grade and poor prognosis." (PMID 37598181, 2023). "In another study done on 155 CRC patients’ overexpression of Beclin 1, a scaffold for the formation of autophagosomes was linked to tumor aggressiveness." (PMID 35912261, 2022). "At present, Beclin-1 is generally considered as a tumor suppressor gene, and the deletion of its allele can be detected in a variety of tumors, while some studies have found that Beclin-1 can promote occurrence and development of tumors." (PMID 35794987, 2022). "Beclin-1 heterozygous-deficient mice presented a high incidence of tumors indicating that autophagy functions as a tumor suppressor process in vivo." (PMID 36291097, 2022). "Loss of Beclin 1 expression defines poor prognosis by promoting anti-apoptotic pathways, whereas overexpression of Beclin 1, being linked with tumor hypoxia and acidity, also defines subgroups of tumors with aggressive clinical behavior." (PMID 36230664, 2022). "In the xenograft nude mice model, ectopic expression of Beclin 1 significantly facilitates tumor growth, whereas autophagy-deficient mutant Beclin 1S90+93A is unable to do so." (PMID 36528652, 2022). "Previous studies showed that BECN1 heterozygous mutant mice were more susceptible to tumor development 42-44." (PMID 36313039, 2022). "Meta-analysis indicated that the elevated Beclin 1 expression is associated with tumor metastasis and a poor prognosis in CRC patients." (PMID 36230664, 2022). "Some studies shown that BECN1 is a haploid-deficient tumor suppressor gene and supported the theory that autophagy can inhibit tumor formation as a tumor suppressor gene." (PMID 34950036, 2021). "BECN1 functions as a tumour‐suppressor gene, and its deficiency is also associated with several neuro‐degenerative diseases." (PMID 34085745, 2021). "The relative expression levels of Beclin-1 and Atg7, which are the key proteins associated with the initial formation of autophagosomes in the tumor tissues of patients." (PMID 33777735, 2021). "The relationship between impaired autophagy and tumour development is best evidenced by inhibition of the latter process in mice (the cancer development was caused by loss of BECN1 gene)." (PMID 33804163, 2021). "Mutated BECN1 results in the reduction of autophagy and augmentation of cell proliferation in cancer cell lines and mice models, suggesting that BECN1 aids in tumour regression." (PMID 33802014, 2021). "We found that Beclin-1 expression was associated with tumor stage and lymph node metastasis, and the expression of Beclin-1 in ESCC tissues was significantly lower than that in adjacent tissues, which suggests that autophagy activity was inhibited in ESCC." (PMID 34257544, 2021). "The studies indicated that mice with monoallelic deletion of the gene encoding becline-1 (Becn1+/−) showed a significant increase in the incidence of spontaneous tumours in compared to mice having both wild alleles." (PMID 33804163, 2021).
tumor (continued). "Autophagy has been connected to tumor suppression via the discovery of monoallelic loss of autophagy gene BECN1 in several types of human cancers such as breast and ovarian cancers." (PMID 34944772, 2021). "The loss of autophagy-related protein Beclin-1 was inversely correlated with histologic grade and tumor stage in EAC patients." (PMID 34252349, 2021). "Tumor tissue analysis showed the increased expression of caspase-6 and -7, associated with apoptosis, and of Beclin 1 and LC3, associated with autophagy, by the combination of gefitinib with curcuminoids." (PMID 32927836, 2020). "Autophagy was initially thought to be a tumor suppressive mechanism because BECN1, key in phagophore formation, is a haploinsufficient tumor suppressor with monoallelic loss in several human breast, prostate, and ovarian cancers." (PMID 33224954, 2020). "By contrast, the loss of just one allele of BECN1 is sufficient to induce tumorigenesis, and therefore, it is suggested as a haploinsufficient tumour suppressor." (PMID 32935427, 2020). "Overall, loss of one allele of Becn1 enhanced tumor initiation and correlated with increased chromosomal alterations in vivo." (PMID 31923184, 2020). "Beclin 1 is a proven autophagy-associated protein that promotes autophagy and plays a tumor-suppressive role in the lysosomal degradation pathway of autophagy." (PMID 32309430, 2020). "By contrast, the loss of just one allele of BECN1 is sufficient to induce tumorigenesis, and therefore it is classified as a haploinsufficient tumor suppressor." (PMID 31877888, 2019). "Existing reports on the prognostic role of autophagy or autophagy-associated proteins such as Beclin-1 in tumor progression are often contradictory." (PMID 30849962, 2019). "Supportive models for this tumor-suppressive action of autophagy are found in hemizygous Beclin-1-deficient mice that lose their autophagic regulatory potential thereby being increasingly susceptible to tumor formation." (PMID 31906235, 2019). "Unexpectedly, allelic loss of the autophagy regulator Beclin-1, significantly delayed tumor development in ATM-null mice." (PMID 29616191, 2018). "Atg5-deficiency, Atg7-deficiency, and Beclin-1 partial deletion can spur spontaneous tumor growth commonly seen in most cancers." (PMID 29988591, 2018). "A variety of proteins, including UV radiation resistance-associated gene (UVRAG) and Bax interacting factor-1 (Bif-1), which associate with BECN1 function as tumor suppressors and positively regulate autophagy." (PMID 30400561, 2018). "In cancer-cell lines and mice models, the loss of BECN1 results in a reduction of autophagy and an increase in cell proliferation, further indicating that BECN1 gene acts as a tumor suppressor." (PMID 30400561, 2018). "Overexpression of Beclin 1, linked with tumor hypoxia and acidity, also defines subgroups of tumors with aggressive clinical behavior, presumably by promoting autophagy." (PMID 28696368, 2017). "Beclin-1, the mammalian orthologue of yeast ATG6, has a central role in autophagic regulation, and has been linked to diverse biological processes including immunity, development, tumor suppression, and lifespan extension." (PMID 28428545, 2017). "Until recently, the BECN1 gene that encodes the Beclin-1 protein was proposed to function as a tumour suppressor gene." (PMID 27444698, 2016). "Other studies indicate that BECN1 represents an important tumor suppressor and an increased BECN1 expression is associated with a favorable prognosis in several cancers." (PMID 26222012, 2016). "Hemizygosity (BECN 1+/-) of BECN1 or knockout of the gene encoding the UVRAG-binding protein BIF-1 (Bax-interacting protein-1) leads to a high incidence of different spectrums of tumor types in mice." (PMID 26965179, 2016).
tumor (continued). "There was a significantly association between cytoplasmic expression of Beclin-1 in tumor and lymphatic invasion (P = 0.0175), whereas nuclear Beclin-1 expression in stroma was associated with positive marginal status (P = 0.0379)." (PMID 25719198, 2015). "Paradoxically, high expression of Beclin 1 was associated with tumor progression in some cancers, as previous described." (PMID 26506105, 2015). "Similar results confirmed the association of low BECN1 expression with ER-negative tumor subtypes when the analyses were confined to tumors with BRCA1 deletions." (PMID 25825707, 2015). "In tumour xenografts, the acetylation-deficient mutant Beclin 1–2KR inhibits cell proliferation and tumour growth." (PMID 26008601, 2015). "BECN1, an autophagy-related gene located on human chromosome 17q21, encodes the protein Beclin-1, which participates in the formation of phages and can inhibit tumor growth by increasing the rate of autophagy." (PMID 25789037, 2015). "Associations between Beclin-1 expression and tumor size, extra-thyroidal extension or nodal metastases at diagnosis were not proven." (PMID 25487826, 2015). "In this study, the underexpression of BECN1 was correlated with poor prognosis, whereas the extensive overexpression of BECN1 was associated with the tumor HIF-1α level and aggressive clinical behavior." (PMID 24723943, 2014). "By multivariate Cox regression analysis, only large tumor size, higher Edmondson grades, late stage and loss of or lower expression of Beclin-1 were identified to be independent prognostic factors for OS (P < 0.05)." (PMID 24885292, 2014). "In mammals, it has been linked to tumor development, since one of the most important macroautophagy-related molecules, Beclin 1 (a Bcl2-interacting protein), is a haploinsufficient tumor suppressor gene." (PMID 25324830, 2014). "Monoallelic loss of the beclin-1 gene on chromosome 17q21 has been reported in 40% to 75% of human breast, ovary, and prostate tumors, suggesting that autophagy represents a tumor suppressor mechanism." (PMID 25328887, 2014). "Log-rank test indicated that the association of high expression of BECLIN 1 in the tumour with a good prognosis was statistically significant." (PMID 25136588, 2014). "For example, allelic loss of Becn1 causes increased tumor development in mice, and the BECN1 gene is deleted in human tumors." (PMID 25313680, 2014). "We found that AGD was 4, 49 and 39 days for control (SCR), ATG5-deficient (ATG5KD) and BECN-1-deficient (BECN-1KD) tumours, respectively." (PMID 24037090, 2014). "Clinical studies have associated poor prognosis and aggressive tumor phenotypes with aberrant expression of Beclin 1 in tumor tissues." (PMID 24260370, 2013). "The mammalian Beclin 1, the ortholog of yeast Atg6/Vps30, is an essential autophagic player that has been linked to diverse biological processes, including development, immunity, tumor suppression and lifespan extension." (PMID 24303007, 2013). "Recently, in vitro studies suggest that loss of one allele of Beclin 1 leads to elevated ROS levels, increases DNA damage and chromosomal instability, and promotes tumor growth in nude mice." (PMID 21611191, 2011). "Survival analysis confirmed the ominous prognostic role of extensive Beclin 1 overexpression, but a similarly poor survival was also showed in tumours with loss of Beclin 1 expression." (PMID 20842118, 2010). "Beclin-1 is often mono-allelically deleted in various carcinomas and its heterozygous disruption in mice caused spontaneous tumours." (PMID 20856861, 2010). "Beclin 1 was mapped to a tumor susceptibility locus approximately 150 kb centromeric to BRCA1 on human chromosome 17q21." (PMID 20230646, 2010).